VPS13A (vacuolar protein sorting 13 homolog A)
Diseases named in the same sentence as VPS13A in open-access papers (continued):
Sharing a sentence is not in itself a finding about the gene and the disease.
chorea-acanthocytosis (continued). "Vacuolar protein sorting 13 homolog A (VPS13A) disease, historically known as chorea-acanthocytosis, is a rare neurodegenerative disorder caused by biallelic mutations in VPS13A, resulting in reduced or absent VPS13A protein." (PMID 37928888, 2023). "Cooperation between VPS13A and XK, which has recently been confirmed by in vitro studies to have scramblase activity, would represent another example of such a partnership, providing clues to mechanisms of disease in chorea-acanthocytosis and McLeod syndrome." (PMID 35994651, 2022). "Two of the mammalian VPS13 isoforms, VPS13A and VPS13D, whose loss-of-function mutations cause Chorea Acanthocytosis and heterogeneous movement disorders including ataxias, respectively, act at contacts between the ER and mitochondria, although they bind to mitochondria via different mechanisms." (PMID 34046249, 2021). "As of 2020, with the help of a large group of international colleagues, we have collected blood samples of more than 700 patients with a clinical suspicion of VPS13A disease (formerly chorea-acanthocytosis, ChAc) or related disorders (Danek, Bader & Miltenberger)." (PMID 34046249, 2021). "Chorea-acanthocytosis (ChAc) is caused by a VPS13A gene mutation leading to marked reduction or absence of VPS13A protein." (PMID 34046249, 2021). "In 1985 Jankovic in particular advocated for the use of “neuroacanthocytosis” rather than of “choreoacanthocytosis” or “Levine-Critchley syndrome” to describe such cases, that in hindsight are characterized by the features of disease due to VPS13A mutations." (PMID 33510935, 2021). "Humans express four different VPS13 paralogs, designated A through D. Mutations in VPS13A, VPS13B, VPS13C and VPS13D are associated with the neurodegenerative disorder Chorea-Acanthocytosis (ChAc), Cohen Syndrome, Parkinson’s Disease, and a form of cerebellar ataxia, respectively." (PMID 34201352, 2021). "Chorea-acanthocytosis (ChAc) is a rare autosomal recessive neurodegenerative disorder caused by VPS13A gene mutations leading to marked reduction or absence of VPS13A." (PMID 37928888, 2023). "Chorea-acanthocytosis (ChAc) is an inherited neurodegenerative movement disorder caused by VPS13A gene mutations leading to the absence of protein expression." (PMID 37928888, 2023). "The VPS13 family is associated with various human diseases; in particular, a loss of VPS13A function disrupts autophagic flux and leads to chorea-acanthocytosis (ChAc), a rare neurodegenerative disease with no known cure." (PMID 32375900, 2020). "In particular, the loss of function of VPS13A leads to chorea-acanthocytosis (ChAc), a rare neurodegenerative disease without available curative treatments." (PMID 30709847, 2019). "We aimed to predict signaling sub-networks possibly involved in the generation of acanthocytes in patients affected by the two core NA disorders, namely McLeod syndrome (MLS, XK-related, Xk protein) and chorea-acanthocytosis (ChAc, VPS13A-related, chorein protein)." (PMID 22355334, 2012). "Since this enzyme is localized in mitochondria, the similar pathological manifestations of PKAN and chorea-acanthocytosis may be related to the importance of both PANK2 and VPS13A in aspects mitochondrial physiology dependent on normal lipid homeostasis." (PMID 34216812, 2021).
McLeod syndrome (16 papers, 2012 to 2026). "This group encompasses autosomal recessive chorea-neuroacanthocytosis (ChAc) and X-linked McLeod syndrome (MLS) with mutations in the VPS13A gene and the XK gene, respectively." (PMID 39183347, 2024). "Finding the interaction between VPS13A and XK is important because mutations in the VPS13A gene manifest clinically similarly to mutations in the XK gene causative of McLeod syndrome." (PMID 35563497, 2022). "In four patients a core neuro-acanthocytosis syndrome was diagnosed: in two patients each from mutations in the VPS13A gene (confirming the diagnosis of VPS13A disease) and from mutations in the XK gene, associated with McLeod syndrome." (PMID 34046249, 2021). "The VPS13A-XK interaction has significant disease implications as mutations in XK result in McLeod syndrome, a neuroacanthocytosis syndrome with similar phenotypes to VPS13A-associated chorea-acanthocytosis." (PMID 33809364, 2021). "Here, we report 12 Italian patients with a molecular diagnosis of NA, nine belonging to five ChAC families (carrying bi-allelic variants of the VPS13A gene) and three belonging to the same family with McLeod syndrome (harboring a deletion of exon 1 of the X-linked XK gene)." (PMID 33652783, 2021). "It was mainly used to characterize ChAc, McLeod syndrome (MLS), and Huntington’s disease-like 2 (HDL2) between 2001–2017, and it is understood that the current understanding of NA includes diseases caused by mutations in the VPS13A and XK genes." (PMID 39119561, 2024). "WES revealed a stop-gain mutation (c.799C > T; p.R267X) in the VPS13A gene while no mutation was found in the XK gene, confirming the patient as a case of ChAc and overruling the possibility of McLeod syndrome." (PMID 37209156, 2023). "Interestingly, it has been recently described that dysregulation of a VPS13A-XK complex is the common basis for ChAc and McLeod Syndrome." (PMID 34046249, 2021). "If used as an overarching term referring only to VPS13A disease and McLeod syndrome, “neuroacanthocytosis” might retain some utility." (PMID 33510935, 2021). "Direct interactions between VPS13A and XK proteins may explain some of the common features between ChAc and McLeod syndrome." (PMID 34046249, 2021).
acanthocytosis (13 papers, 2017 to 2024). "The role of the PH domain in human VPS13 proteins has not been studied, but mutations resulting in truncation of the VPS13A PH domain are causative for chorea-acanthocytosis suggesting an important function for this domain." (PMID 33809364, 2021). "The evolutionary conserved VPS13A gene is associated with the neurodegenerative disorder Chorea Acanthocytosis." (PMID 34046249, 2021). "To obtain confirmatory molecular information for the clinical working diagnosis of chorea‐acanthocytosis, we performed a Western blot to detect the VPS13A protein." (PMID 32056394, 2020). "However, acanthocytosis has only been identified in VPS13A disease giving rise to remarkable phenotypic similarities with XK disease, that is a genetically distinct disorder." (PMID 39416949, 2024). "In patients with neurodegenerative disease due to bi-allelic mutations of VPS13A (“chorea-acanthocytosis”), neither chorea nor acanthocytes are obligatory or invariable features." (PMID 33510935, 2021). "Blood smears may demonstrate red blood cell acanthocytosis, which lead to the assumption of so-called neuroacanthocytosis syndromes, along with the VPS13A disease choreoacanthocytosis (ChAc), with which MLS shares a considerable phenotypic overlap." (PMID 34046249, 2021). "As the localizations of VPS13A as LTP at MCSs has been gradually revealed, disruption of lipid exchange at one or more of these contacts is thought to be the basis for neurodegeneration and acanthocytosis in ChAc." (PMID 39659962, 2024).
Chorea (12 papers, 2020 to 2025). Chorea (Greek for 'dance') refers to widespread arrhythmic involuntary movements of a forcible, jerky and restless fashion. "The pattern of brain involvement in MLS explains the distinctive clinical manifestations, with chorea as the cardinal symptom, as seen in other diseases marked by neuronal loss and gliosis in the basal ganglia in particular, striatal involvement in VPS13A disease and HD." (PMID 40898647, 2025). "VPS13A disease is a rare, autosomal recessive neurodegenerative disorder that is characterized by a spectrum of movement disorders (chorea, dystonia, tics, sometimes parkinsonism), seizures, as well as psychiatric, cognitive, and behavioral changes." (PMID 37928888, 2023). "Further genetic investigation, including SETX and other chorea-related genes (i.e., ADCY5, PRNP, and VPS13A) are needed, but are lacking due to limitations of laboratory conditions." (PMID 36596053, 2022).
neuroacanthocytosis syndromes (10 papers, 2021 to 2026). "The neuroacanthocytosis syndromes, VPS13A and XK diseases, are characterized by neurological, cognitive, and psychiatric symptoms attributable to progressive degeneration of the basal ganglia, in addition to other features including seizures, peripheral neuropathy and myopathy." (PMID 41522673, 2026).
Parkinson disease (9 papers, 2020 to 2026). A progressive degenerative disorder of the central nervous system characterized by loss of dopamine producing neurons in the substantia nigra and the presence of Lewy bodies in the substantia nigra and locus coeruleus. "In the context of neurodegeneration, it is of interest that a WWE domain is present within the structure of VPS13A, as well as of VPS13C, whose mutations also result in neurodegeneration (Parkinson’s disease)." (PMID 35994651, 2022).
epilepsy (5 papers, 2021 to 2024). A brain disorder characterized by episodes of abnormally increased neuronal discharge resulting in transient episodes of sensory or motor neurological dysfunction, or psychic dysfunction. "Further family verification revealed a homozygous genotype of his brother (with a PMH of epilepsy) and a heterozygous genotype of his parents and sister (who were all asymptomatic) in the c.2061dup mutation of VPS13A." (PMID 38933328, 2024). "Autosomal recessive VPS13A disease is caused by mutations in the Vacuolar Protein Sorting 13 Homolog A (VPS13A) gene and may present with progressive cognitive impairment, psychiatric symptoms, various movement disorders, muscle weakness, and epilepsy." (PMID 39091345, 2024). "Whether the variant at C-terminus of VPS13A is responsible for the epilepsy phenotype remains to be delineated." (PMID 37209156, 2023).
Dystonia (4 papers, 2017 to 2024). An abnormally increased muscular tone that causes fixed abnormal postures. "Feeding dystonia, a hallmark of VPS13A disease, is particularly challenging to treat as reported here." (PMID 39416949, 2024).
Huntington disease (4 papers, 2021 to 2024). Huntington disease (HD) is a rare neurodegenerative disorder of the central nervous system characterized by unwanted choreatic movements, behavioral and psychiatric disturbances and dementia. "VPS13A disease and Huntington’s disease (HD) are two basal ganglia disorders that may be difficult to distinguish clinically because they have similar symptoms, neuropathological features, and cellular dysfunctions with selective degeneration of the medium spiny neurons of the striatum." (PMID 38903599, 2024).
male infertility (4 papers, 2021 to 2025). The inability of the male to effect fertilization of an ovum after a specified period of unprotected intercourse. "A previous study indicated that a Vps13a deficiency causes male infertility characterized by reduced sperm motility, probably due to abnormal mitochondrial function in the sperm midpiece." (PMID 39063018, 2024). "In line with this, an association between mitochondrial dysfunctionality and male infertility as a result of a diminished sperm motility has been reported for several knockout models (VPS13A, Tppp2, Gykl1, and Gk2)." (PMID 34765607, 2021). "The Vps13a KO mice exhibited male infertility, abnormal sperm morphology, and increased reticulocytes in blood smear tests." (PMID 39063018, 2024). "Our data indicate that Vps13a KO mice are valuable models for studying male infertility and some hematological aspects of ChAc." (PMID 39063018, 2024). "Since we also observed male infertility in the Vps13a KO mice on the C57BL/6N background, we examined sperm using transmission electron microscopy (TEM)." (PMID 39063018, 2024). "The Vps13a KO mice in the C57BL/6 strain exhibited male infertility and abnormal sperm morphology, consistent with previous reports on Vps13a KO mice in other mouse strains." (PMID 39063018, 2024). "We observed male infertility, abnormal sperm morphology, and increased reticulocytes in peripheral blood from the Vps13a KO mice; however, there were no significant abnormalities in the forebrain of KO mice." (PMID 39063018, 2024). "Vps13a KO mice were born with mendelian distribution and did not exhibit any obvious phenotypic defects except male infertility and immunoblot analysis of cortical brain tissue from these mice confirmed the absence of VPS13A, as previously reported for the same mouse line." (PMID 40956846, 2025). "Vps13a KO mice were born with Mendelian distribution and did not exhibit any obvious phenotypic defects except male infertility and immunoblot analysis of cortical brain tissue from these mice confirmed the absence of VPS13A, as previously reported for the same m line." (PMID 40463036, 2025).
Epileptic seizures (2 papers, 2020 to 2024). "Epileptic seizures were also present in families with NAGLU, SLC5A2, POLR3B, and VPS13A mutations, and behavioral and psychiatric symptoms were observed in a family with POLR3B mutations (Fam 03)." (PMID 31969655, 2020).
gastric cancer (2 papers, 2014). A primary or metastatic malignant neoplasm involving the stomach. "VPS13A codes for vacuolar sorting proteins, and its loss was observed in colorectal and gastric cancers with high microsatellite instability." (PMID 25006670, 2014). "As observed in this study, VPS13A was expressed in SP cells and was concluded to be associated with a T category cancer and lymph node metastasis of gastric cancer." (PMID 25379943, 2014). "A past study found that frameshift mutations of VPS genes, along with loss of expression of VPS13A proteins, are common in gastric cancers with high microsatellite instability and suggests that these alterations may contribute to the development of cancer." (PMID 25379943, 2014).
glioma (2 papers, 2014 to 2025). A benign or malignant brain and spinal cord tumor that arises from glial cells (astrocytes, oligodendrocytes, ependymal cells). "Cloning insertions from these SB-induced gliomas identified Sfi1, Csf1, Mkln1, Vps13a and Fli1 as common insertion sites (CISs) which are chromosomal regions that are insertionally mutated in more tumors than would be expected by random chance and represent candidate glioma genes." (PMID 25423036, 2014).
Sepsis (2 papers, 2019 to 2022). Sepsis is defined as life-threatening organ dysfunction caused by a dysregulated host response to infection. "Additionally, Scherag and colleagues found that the top ranking variants associated with 28-day mortality from sepsis in their study were located in the Vacuolar Protein Sorting 13 Homolog A (VPS13A) gene." (PMID 36335405, 2022).
basal ganglia disorder (1 paper, 2024). A disease involving the basal ganglia. "Further experiments are necessary to evaluate the role of the VPS13A function in mediating these convergent mechanisms that determine MSN-specific vulnerability in basal ganglia disorders." (PMID 38903599, 2024).
leukemia (1 paper, 2022). A malignant (clonal) hematologic disorder, involving hematopoietic stem cells and characterized by the presence of primitive or atypical myeloid or lymphoid cells in the bone marrow and the blood. "We next determined the effect of SNDX-5613 on in vivo leukemia-initiating potential of primary PD AML cells harboring MLL-AF9 plus FLT-3 N676T, as well as mutations in KMT2C, KMT2D, NOTCH2, IRF8, ARID1A, VPS13A, and ABCA7, which were determined by whole-exome sequencing." (PMID 35017466, 2022).
lipid storage myopathies (1 paper, 2026). "One patient's muscle biopsy revealed marked myopathic changes with internalized nuclei and fiber size variation, as well as multiple fibers with lipid storage in Oil Red staining, which has not yet been reported in VPS13A disease but is typical for lipid storage myopathies." (PMID 41030128, 2026).
type 2 diabetes (1 paper, 2020). "We investigated the role of VPS13A and VPS13C in GLUT4 translocation to the plasma membrane, as the VPS13C gene locus has been linked to type 2 diabetes risk and glycaemic traits." (PMID 33087848, 2020).
neurodegenerative disease (14 papers, 2016 to 2026). A disorder of the central nervous system characterized by gradual and progressive loss of neural tissue and neurologic function. "Chorea acanthocytosis (ChAc) is an ultrarare inherited neurodegenerative disease caused by a VPS13A gene mutation, resulting in the loss of the VPS13A protein." (PMID 41522673, 2026). "VPS13A is a lipid transfer protein localized at different membrane contact sites between organelles, and mutations in the corresponding gene produce a rare neurodegenerative disease called chorea‐acanthocytosis (ChAc)." (PMID 37163371, 2023). "ChAc is an ultra-rare neurodegenerative disease caused by mutations in the VPS13A gene (vacuolar protein-sorting protein 13)." (PMID 34046249, 2021). "Chorea acanthocytosis (ChAc), an ultra-rare devastating neurodegenerative disease, is caused by mutations in the VPS13A gene, which encodes for the protein chorein." (PMID 32151030, 2020). "A loss of VPS13A (also called chorein) expression leads to the rare neurodegenerative disease chorea-acanthocytosis (ChAc)." (PMID 27329800, 2016). "Furthermore, we present first quantitative measurements of XK and VPS13A protein levels in a healthy control cohort, in the related disorders and other neurodegenerative diseases." (PMID 41522673, 2026). "VPS13A was previously identified as a key factor in various human neurodegenerative diseases." (PMID 35880571, 2022). "Thus, we showed robust differentiation to mature midbrain and hindbrain neurons, which was not affected by mutations in the VPS13A gene, fitting to the nature of a neurodegenerative disease." (PMID 32151030, 2020).
neurological disorder (9 papers, 2017 to 2024). "Mutations in each of them cause severe neurological disorders: chorea-acanthocytosis (VPS13A), Cohen syndrome (VPS13B), Parkinson’s disease (VPS13C), and several neurological disorders or embryonic lethality in the case of complete loss-of-function (VPS13D)." (PMID 39331042, 2024). "There are four members of the Vps13 family—Vps13a, Vps13b, Vps13c, and Vps13d—and mutations in each gene cause distinct neurological diseases." (PMID 39063018, 2024). "CIH was also associated with VPS13A, a gene involved in a severe neurological disorder characterized by hyperkinetic movements." (PMID 33159041, 2020). "VPS13A gene is associated with development of a neurological disorder." (PMID 34900593, 2021).
movement disorder (6 papers, 2019 to 2024). Neurological conditions resulting in abnormal voluntary or involuntary movement, which may impact the speed, fluency, quality and ease of movement. "The question remains why loss of VPS13A leads to ChAc, a movement disorder mostly presenting in the third decade of the patient’s life." (PMID 30741634, 2019). "This study highlights, that VPS13A should be considered a genetic cause of epilepsy, particularly, but not necessarily, if additional symptoms such as movement disorders, neuromuscular involvement or cognitive-psychiatric disorders are present." (PMID 37928888, 2023).
cancer (5 papers, 2014 to 2024). A tumor composed of atypical neoplastic, often pleomorphic cells that invade other tissues. "These included several candidate tumor suppressor genes, such as ABLIM1, CYFIP2, VPS13A, SERPINI1, TET2, HTRA4, UBE2L6, as well as oncogenes/genes implicated as biomarkers in other cancers, such as FAM65B and TCF7L2." (PMID 27385100, 2016).
genetic disease (3 papers, 2015 to 2022). "Loss of function mutations in chorein or vacuolar protein sorting-associated protein 13A (VPS13A) have been found in patients with a rare hereditary genetic disorder called chorea-acanthocytosis (ChAc)." (PMID 35098253, 2021).